BHLHE40 (basic helix-loop-helix family member e40)
Diseases named in the same sentence as BHLHE40 in open-access papers (continued):
Sharing a sentence is not in itself a finding about the gene and the disease.
tumor (continued). "In human tumor cells, there are functional differences in their roles: BHLHE40 induces apoptosis and epithelial-mesenchymal transition (EMT), whereas BHLHE41 inhibits them." (PMID 36412639, 2022). "For example, scRNA-seq analyses were performed on the immune tumour microenvironment in colorectal cancer patients, providing evidence of the importance of Bhlhe40+ Th1-like CD4+ T cells in anti-tumour immunity and immunotherapy." (PMID 34621670, 2021). "With regard to HCC, BHLHE40 was shown to be activated by HIF-1α, suggesting its role in adaptation to a hypoxic microenvironment associated with tumor progression." (PMID 34045534, 2021). "While BHLHE40 localized to the cytoplasm in hepatocytes of normal liver, HCC tissues showed high nuclear localization of BHLHE40, suggesting that nuclear BHLHE40 had a tumor promoting effect." (PMID 32577154, 2020). "Elevated expression of BHLHE40 was observed in endothelial, fibroblasts and inflammatory cells of the patients in addition to tumor cells." (PMID 32577154, 2020). "Future studies should compare the transcriptional targets of BHLHE40 in tumors where it is tumor suppressive and compare them to tumors where it is oncogenic in order to determine the mode of action of this transcription factor in cancer." (PMID 32577154, 2020). "BHLHE40 also negatively correlated with age, tumor embolus, depth of invasion of ESCC, lymph metastasis status and pathological tumor lymph node metastasis stage (pTNMs)." (PMID 32577154, 2020). "Overall, these studies demonstrate that one way by which BHLHE40 suppresses tumor growth is by targeting JAK/STAT signaling." (PMID 32577154, 2020). "The expression patterns of BHLHE40 and its impact on tumor development are tumor type-specific - it is suppressed in some types of cancer and overexpressed in others." (PMID 32577154, 2020). "Many different types of brain cancers have been characterized, and in almost all of them, BHLHE40 expression has been shown to be higher than in surrounding non-tumor tissue." (PMID 32577154, 2020). "A common theme that has emerged in the review of the literature is that BHLHE40 promotes cancer when it has anti-apoptotic functions while it acts as a tumor suppressor when it promotes apoptosis." (PMID 32577154, 2020). "BHLHE40 expression correlated positively with tumor grade (p = 0.01), and with various angiogenic factors." (PMID 32577154, 2020). "In certain cancers, BHLHE40 is increased in tumors compared to normal tissue, but as the tumor progresses, its levels decrease." (PMID 32577154, 2020). "BHLHE40 expression was critical for tumor-infiltrating lymphocytes (TIL) reinvigoration following anti-PD-L1 blockade." (PMID 32577154, 2020). "Many excellent reviews exploring the connection between the circadian rhythm and cancer has been written, including from our group; many of these have explored the tumor-suppressive role of BHLHE40 in the cross-talk between circadian rhythm and cancer." (PMID 32577154, 2020). "Studies reveal that BHLHE40 expression is regulated by multiple pathways, which are either tumor promoting or suppressing." (PMID 32577154, 2020). "In EC cells, the MIR130 family promoted EMT and tumor cell invasion by suppressing the expression of BHLHE40/41." (PMID 31384392, 2019). "Tumor suppression by BHLHE40 and/or BHLHE41 has been reported to be mediated by the regulation of cyclins, senescence, epithelial-to-mesenchymal transition (EMT), hypoxia-inducible factors, MAPK1, RELA, or NOTCH1." (PMID 31384392, 2019). "As suggested tumor suppressors, the expression of BHLHE40/41 was downregulated in cancer cases at advanced stages." (PMID 31384392, 2019). "For instance, BHLHE40 was reported to activate transcription of pro-survival factors in tumor cells, including BIRC5 and DeltaNp63." (PMID 30285805, 2018). "Other relevant transcripts that were significantly induced in the tumor CD45+ cells include Bhlhe40, Eomes S1PR1, TIM3 and CX3CR1." (PMID 29423108, 2018).
tumor (continued). "This study reveals a novel role of BHLHE40 in promoting tumor cell survival and migration by regulating HBEGF secretion." (PMID 30285805, 2018). "Together, these results suggest that BHLHE40 is required for tumor cells to survive in the circulation and establish metastatic foci in the lungs." (PMID 30285805, 2018). "The expression of BHLHE40 by tumor-specific cytolytic T cells may increase the recruitment of macrophages." (PMID 40027748, 2025). "Moreover, the upregulation of BHLHE40 expression has been correlated with poor differentiation of GC, suggesting its crucial role in tumor development." (PMID 40413527, 2025). "In tumor cells, BHLHE40 may affect cell metabolism and proliferation by regulating the expression of certain genes." (PMID 40413527, 2025). "The findings suggest that inhibiting SREBF1 with fatostatin could suppress PCa tumor growth, especially in cases with high BHLHE40 expression." (PMID 38064101, 2024). "Then, we conducted SCENIC analysis to explore the transcriptional regulation driving the acquisition of the cholesterol-related Tumor-Modifying state in neutrophils which revealed activation of BHLH family transcription factors (BHLHE40, ETV5, OLIG2, and SREBF1) within the Neu-T-CCL3 cluster." (PMID 38822440, 2024). "Knockdown suggests that BHLHE40 mediates SAL-induced cellular senescence including tumor spheroids." (PMID 38902772, 2024). "Therefore, a strategy to activate BHLHE40 signaling would be an effective way to control tumor development." (PMID 38301894, 2024). "In addition, BHLHE40 expression was compared between tumor and adjacent samples derived from two distinct GEO datasets." (PMID 38902772, 2024). "Another element strongly differing between superclusters was BHLHE40, a member of the bHLH TF family, which was found strongly downregulated in supercluster A. BHLHE40 has been reported to induce EMT as well as tumour growth and lung metastases via HBEGF exosomal release." (PMID 38066300, 2023). "BHLHE40, as a pro-oncogenic transcription factor, could be involved in regulating the transcription of a variety of genes affecting tumor progression." (PMID 37773521, 2023). "BHLHE40 overexpression increased the sphere formation capacity of tumor cells." (PMID 37377917, 2023). "In addition, paired tumor tissues and normal tissues in PAAD from TCGA dataset were performed that BHLHE40 was higher expressed in tumor tissues." (PMID 37773521, 2023). "To investigate the expression of BHLHE40 in pan-cancer, we used TCGA and GTEX database including tumor tissues and normal tissues from 33 types of cancer to reveal that BHLHE40 were highly expressed in 7 of 33 tumor tissues compared to para-cancer tissues and were downregulated in 13 of 33 cancers." (PMID 37773521, 2023). "In addition, promoted BHLHE40 switches off the IL-10 inflammatory “brake” and stimulates the proliferation of (tumor) tissue-infiltrating lymphocytes and inhibits antiviral THαβ cells, which are driven by IL-10 and IFNα/β." (PMID 35723340, 2022). "BHLHE40 is a transcription factor with roles in Th1 and Th17 effector and pathogenic functions, as well as supporting mitochondrial fitness and metabolism in CD8 + tissue-resident memory cells and tumor-infiltrating lymphocytes." (PMID 35945487, 2022). "In contrast, cytoplasmic BHLHE40 bound to and stabilized cyclin E, thereby preventing its nuclear entry and inhibiting cell cycle progression, thus, an increase in cytoplasmic BHLHE40 is tumor suppressive." (PMID 32577154, 2020). "In these examples, therefore, BHLHE40 was involved in tumor suppression downstream of TGF-β." (PMID 32577154, 2020). "Depending on the pathway regulating its expression, and its cooperation with that pathway, BHLHE40 may be induced to either promote tumor progression or tumor regression." (PMID 32577154, 2020). "BHLHE40-KD substantially reduced lung metastasis in mice with similar primary tumor burdens." (PMID 30285805, 2018).
tumor (continued). "BHLHE40 expression is directly activated by HIF1A in a variety of tumor cells under hypoxia." (PMID 30285805, 2018). "Although EMT is associated with tumor angiogenesis, this study did not directly explore whether Bhlhe40 regulates tumor angiogenesis." (PMID 39062912, 2024). "Bhlhe40 is induced by various stress stimuli, such as hypoxia, tumor necrosis factor-α, irradiation, paclitaxel, and transforming growth factor-beta (TGF-β), and participates in several pathogenic processes, including inflammation, apoptosis, tumor growth, and fibrosis." (PMID 36304536, 2022). "Furthermore, this study showed tumour-specific T cell responses, with enrichment and clonal expansion of pro-inflammatory CXCL13+ BHLHE40+ TH1-like cells in tumours with microsatellite instability, but moderate enrichment for Th17 cells in those with microsatellite stability." (PMID 34848830, 2021). "However, the degree of BHLHE40 nuclear staining decreased with tumor progression from well-differentiated to moderately and poorly differentiated tumors, indicating a dichotomy of BHLHE40 function in tumor initiation and in tumor progression." (PMID 32577154, 2020). "Thus, BHLHE40 may have both tumor promoting and suppressive roles depending on the downstream targets that they affect." (PMID 32577154, 2020). "Loss of BHLHE40 was correlated with poor differentiation (p = 0.005) and high p-TNM stage (p = 0.002) while BHLHE40 expression negatively correlated with cyclin D1 expression (p = 0.014), suggesting that BHLHE40 may act as a tumor suppressor in NSCLC." (PMID 32577154, 2020). "Moreover, in some tumors, BHLHE40 appears to have a bimodal function – it is upregulated during tumor initiation, whereas its expression is lost during tumor progression, exhibiting a significant decrease in expression from well-differentiated to poorly differentiated tumors." (PMID 32577154, 2020). "TMX4, ALPL, PTX3, BHLHE40, TNFRSF12A and CST3 demonstrated significant overexpression in LUSC tumour tissues, whereas CLDN1, VKORC1 and ADD3 exhibited significant underexpression in the HPA database." (PMID 38520221, 2024). "Since the KD of BHLHE40 significantly reduces the CCNG2 mRNA it suggests that BHLHE40 up-regulates CCNG2 expression and the atypical CCNG2 is part of the BHLHE40 tumor suppressive pathway." (PMID 38902772, 2024). "Specifically, BHLHE40 was expressed in 73% of tumour tissues, while IL18 was universally present in 100% of tumours." (PMID 38254861, 2024). "In vitro experiments confirmed the function of BHLHE40, with respect to promoting cell migration and invasion via the EMT process, enhancing the stemness of tumor cells, and inhibiting anti-tumor immunity via the promotion of CD8+ T-cell apoptosis." (PMID 37377917, 2023). "Specifically, in the tumour region, we observed enrichment of PPIB and UGT2B15 and IFI27, NDRG1, BHLHE40 and VEGFA." (PMID 35109839, 2022). "BHLHE40, another BHLH family member, is highly expressed by TH1-like tumor-infiltrating CD4+ T cells, a population enriched in the microsatellite-instable subtype." (PMID 35806162, 2022). "NDRG1, BHLHE40 and VEGFA, which were found in tumour cluster B, mainly affect tumour proliferation, metastasis and invasion." (PMID 35109839, 2022). "As an example, the transcription factor Bhlhe40 was shown to maintain the mitochondrial fitness and metabolism of TRM cells and tumor infiltrating cells (TIL), where the expression of Bhlhe40 is selectively upregulated." (PMID 34440651, 2021). "Thus, BHLHE40-mediated tumor suppression can be traced to inhibition of oncogenic factors such as STAT1, whereas BHLHE40-mediated promotion of tumor progression may be traced to the activation of the PI3K/Akt/mTOR pathway and the upregulation of pro-survival factors such as survivin and clusterin." (PMID 32577154, 2020).
tumor (continued). "The BHLHE40 (DEC1/Stra13) is a well-known basic helix-loop transcription factor and has been shown to play major roles in cell proliferation, circadian rhythm, tumor progression and has been shown to be overexpressed in papillary renal cell carcinoma." (PMID 31575031, 2019). "The resulting surge in glycolytic activity, prompted by BHLHE40 and GRIN2D, not only sustains tumor cell survival and proliferation but also correlates with poor histological differentiation and more aggressive tumor phenotypes, thus contributing to the overall malignancy of GC." (PMID 41171531, 2026). "Similarly, the transcription factor BHLHE40 reportedly enhances AMPK signaling by downregulating the phosphatase PPM1F, shifting tumor metabolism from glycolysis to oxidative phosphorylation." (PMID 40806980, 2025). "Through single-cell regulatory network inference and clustering (SCENIC) analysis, they identified BHLHE40 as a key transcriptional driver of TAN-1 differentiation, while functional validation of LDHA established its critical role in immunosuppression and tumor promotion." (PMID 41007733, 2025). "The atypical cyclin CCNG2 (Cyclin G2) acting as a tumor suppressor, is identified here as a novel downstream direct target gene of both BHLHE40 and AR by ChIP-seq and RNA-seq to mediate SAL-induced cellular senescence and linking clock genes with tumor suppression." (PMID 38902772, 2024). "Notably, TMX4, ALPL, PTX3, BHLHE40, TNFRSF12A and CST3 demonstrated significant overexpression in LUSC tumour tissues, whereas CLDN1, VKORC1 and ADD3 exhibited significant underexpression." (PMID 38520221, 2024). "In addition, Bhlhe40 has been shown to be a key regulator of CD8+ TRM formation and function, as deletion of Bhlhe40 significantly reduces CD8+ TRM formation and attenuates the anti-tumor activity of CD8+ T cells." (PMID 38954030, 2024). "EEF1AKMT3, BHLHE40, and HMGB2 were activated in 11 tumor-related clusters of P128T." (PMID 37985711, 2023). "BHLHE40 is activated under hypoxic conditions by HIF-1α in HCC, stimulating tumour progression." (PMID 35109839, 2022). "The efficacy of the PD-L1 blockade in reinvigorating tumor-infiltrating TRM cells depends on Bhlhe40, and Bhlhe40 might therefore constitute a nexus between immunomodulatory signals, metabolism, and functionality of tissue-resident T cell populations." (PMID 33467606, 2021). "Thus, BHLHE40 regulated tumorigenesis downstream of TGF- β in a context-dependent manner, upregulating tumor growth in some cases, downregulating it in others." (PMID 32577154, 2020). "Notably, TRIM31 (logFC = 1.14), ANXA1 (logFC = 1.05), GBP1 (logFC = 1.01), BIRC3 (logFC = 0.99), APOL1 (logFC = 0.97), IL18 (logFC = 0.94), ANXA2 (logFC = 0.89), BHLHE40 (logFC = 0.83), and EPHA2 (logFC = 0.75) exhibited significant upregulation in tumour tissues." (PMID 38254861, 2024). "The implication of Bhlhe40 in regulating tumor angiogenesis has not been explored yet." (PMID 39062912, 2024). "In this context, BHLHE40 enforces efficient expression of cytokines such as IFN-γ, which could provide a protective role against T cell exhaustion, such as what has been described for CD8+ tumor infiltrating T cells." (PMID 34305917, 2021). "However, in the tumor, increased expression was mostly confined to areas of necrosis, while in morphologically viable cells, BHLHE40 was absent." (PMID 32577154, 2020).
cancer (46 papers, 2010 to 2026). A tumor composed of atypical neoplastic, often pleomorphic cells that invade other tissues. "In the current study, BHLHE40 expression was negatively associated with many different types of T cells and suppression of anti-cancer immune responses." (PMID 37377917, 2023). "The factors KDM4C and BHLHE40 were found to be overexpressed only in the tumors with c-met mutation, validating the use of iPSC technology for the analysis of these hereditary cancers." (PMID 31575031, 2019). "Cancer is caused by various factors, and BHLHE40’s role may be defined by the role of the protein in signaling related to these factors." (PMID 32577154, 2020). "In cancer biology, BHLHE40 has been reported to promote colon cancer cell growth and migration by upregulating INHBA." (PMID 40413527, 2025). "Regulator of G-protein signaling 16 (RGS16) has been found to be correlated with the malignant progression of various cancers, and BHLHE40 is highly expressed in GC." (PMID 40413527, 2025). "Bhlhe40 is also required to maintain cell survival in cancer cells and lung-resident helper T cells that exhibit both Tfh and TRM characteristics." (PMID 40906156, 2025). "Our investigation exhibited that, in the TCGA and GTEx databases, BHLHE40 expression was elevated in multiple cancers compared to nearby healthy tissues." (PMID 37773521, 2023). "In our study, The Cancer Genome Atlas (TCGA), Genotype-Tissue Expression (GTEX) datasets was used to perform Kaplan–Meier (KM) survival and ROC analyses to explore BHLHE40 expression and clinical significance in several cancers." (PMID 37773521, 2023). "Bhlhe40, also known as DEC1, Stra13, and SHARP2, has many physiological and pathological functions, such as in cellular differentiation, circadian rhythm, immunity, and cancer." (PMID 36412639, 2022). "BHLHE40 role in cancer is unclear although some studies reported the activation of its expression directly by HIF1α in a variety of cancer cells." (PMID 33602983, 2021). "It has been reported that BHLHE40 can participate in the occurrence and development of cancer, but its role in the regulation of proliferation and oxidative stress in VSMC is still unclear." (PMID 34917665, 2021). "Among the identified DEGs, 5 candidate cancer-induced genes including BHLHE40, AREG, SOCS1, CCL5 and DDIT4 were selected for external validation on an independent set of PBMC samples of patients with various stages of HCC." (PMID 34045534, 2021). "In this article, we will investigate which cellular functions of BHLHE40 are involved in the differential effects of this transcription factor in different types of cancers." (PMID 32577154, 2020). "This contrast can be explained by investigation of the downstream targets of BHLHE40 in cancers where it either promotes or inhibits apoptosis." (PMID 32577154, 2020). "Taken together, these studies indicate that an increase or decrease in BHLHE40 in cancer needs to be qualified by the localization of the protein." (PMID 32577154, 2020). "In this article, we discuss the role of BHLHE40 in oncogenesis, since it is overexpressed in some cancers and suppressed in others." (PMID 32577154, 2020). "This study is the first to report a novel mutual regulation among BHLHE40/41 and miRNAs in cancer cells." (PMID 31384392, 2019). "Hypoxia, a primary driving force of cancer metastasis, induces the expression of BHLHE40, a transcription regulator." (PMID 30285805, 2018). "BHLHE40 is deregulated in a wide variety of cancers and impairs the DNA mismatch repair mechanism by repressing the expression of MLH-1." (PMID 27802351, 2016). "Research has indicated that BHLHE40 participates in the onset and development of various cancers." (PMID 40413527, 2025).